NFE2L2 (NFE2 like bZIP transcription factor 2)
Diseases named in the same sentence as NFE2L2 in open-access papers (continued):
Sharing a sentence is not in itself a finding about the gene and the disease.
cancer (continued). "Likewise, enrichment of factors linked to activated Nfe2l2 are associated with poor survival of head and neck SCC and LUAD, but that is not the case for LUSC and other cancers." (PMID 31221127, 2019). "Some factors identified (e.g., NF-κB, STAT3, FOS) are known to be involved for transformation in our model, others (e.g., CEBPB, HIF1a, ETS2, FHL2, TCF7L2, and NFE2L2) have been described as oncogenes in other settings, and some proteins (BHLHE40 and MAFB) have not been well linked to cancer." (PMID 29802342, 2018). "However, the roles of NFE2L2 in human pan-cancer have not been identified, and whether it can be used as a biomarker is still unknown." (PMID 33101586, 2020). "Many of these genes, including KEAP1, HNF1A, NFE2L2 and LRRK2, have implied roles in cancer but no strong mechanistic links to date (Discussion)." (PMID 30803482, 2019).
tumor (287 papers, 2012 to 2026). "Inactivating mutations in KEAP1 or activating mutations in NFE2L2 lead to constitutive activation of this pathway, allowing tumor cells to neutralize reactive oxygen species (ROS) and withstand oxidative stress induced by SBRT or systemic therapy." (PMID 40725389, 2025). "In general, the literature regarding mutations in KEAP1 as a tumor suppressor gene appears to be more extensive than that concerning NFE2L2." (PMID 39061847, 2024). "To examine the clinical value of Nrf-2, we investigated the associations between the level of NFE2L2 mRNA and clinicopathological features (i.e. tumor size, histological subtype, tumour grade, stage, HER2 status or age at diagnosis)." (PMID 38745155, 2024). "Targeting NFE2L2-dependent AIFM2 expression has shown potential in enhancing ferroptosis-mediated tumor suppression, especially in lung cancer cells deficient in KEAP1." (PMID 39534872, 2024). "According to a previous study, it has been suggested that the tumor-specific OS-related gene NFE2L2 (Nrf2) is strongly associated with highly exhausted TI T cells." (PMID 39169624, 2024). "We recently published a transcriptomic 46-gene signature, the K1N2 score, that robustly predicted KEAP1/NFE2L2 mutation status but also outperformed mutation testing with respect to survival and tumor hypoxia prediction." (PMID 39528799, 2024). "Previous studies have shown that MET, encoded by the HGFR gene, NRAS, a known RAS family oncoprotein, and NFE2L2 promote tumor growth and metastasis in HCC, and their somatic mutation can cause liver carcinogenesis." (PMID 34543520, 2022). "This oversight is probably due to the fact that the rate of somatic mutation in both KEAP1 and NFE2L2 is low in CRC in comparison to the previously studied tumour types." (PMID 34573012, 2021). "Mutations in either KEAP1 or NFE2L2 were found only in KRAS-driven tumor in our cohort and were associated with upregulation of all 3 AKR genes." (PMID 34344431, 2021). "The most obvious way of treating tumours harbouring mutations in NFE2L2 or KEAP1 is with drugs that inhibit NRF2 activity, and a range of small molecules have been reported to possess this ability." (PMID 33276631, 2020). "Several recent studies reported that HBL is a genetically simple tumor with an average of 2.9 mutations per tumor predominately in β-catenin and NFE2L2 genes and in the Wnt pathway." (PMID 30271949, 2018). "In tumour cells, mutations of NFE2L2 were reported to increase resistance to oxidative stress, and promote tumour growth." (PMID 29127303, 2017). "Fifteen lncRNAs (10 genic and 5 intergenic) were identified here as consistently induced in tumours with NFE2L2 gain-of-function mutations." (PMID 28959951, 2016). "This provides mechanistic insight into our finding that human tumours with NFE2L2 gain-of-function mutations display increased expression of LINC00942." (PMID 28959951, 2016). "In the training set (METABRIC dataset, consisting of 1942 patients) we identified associations between NFE2L2 mRNA expression levels and the patient’s age (P < 0.001), tumour histology (P = 0.001), menopausal status (P = 0.003) and HER2 status (P = 0.041)." (PMID 27770790, 2016). "One research group, for example, reported an association between high NFE2L2 expression and aggressive tumour behaviour." (PMID 27770790, 2016). "Nuclear factor erythroid-2-related factor 2 (NFE2L2) is a transcription factor associated with resistance to chemotherapy and increased tumor growth." (PMID 26247201, 2015). "We then developed a risk scoring system based on NFE2L2 gene expression profiling and designated 50 tumor-associated genes as the NFE2L2-associated molecular signature (NAMS)." (PMID 26596768, 2015). "Additionally, mutations in CUL3 or NFE2L2 are present in about 1% of ccRCC tumours according to TCGA data." (PMID 39707614, 2025).
tumor (continued). "However, in certain tumours this pathway is constitutively activated due to gain-of-function mutations in NFE2L2 (encoding NRF2) or loss-of-function alterations in KEAP1 or CUL3, promoting cell proliferation and drug resistance." (PMID 40849356, 2025). "Additionally, research has shown that mutations in the NFE2L2 gene can disrupt its tumor‐suppressive functions, correlating with poorer prognoses." (PMID 39415846, 2024). "Another study suggested that high NFE2L2 expression is associated with aggressive tumor behavior." (PMID 38221932, 2024). "Mutations in NFE2L2 could cause the excessive intracellular accumulation of NFE2L2 protein and the subsequent activation of downstream oncogenes resulting in tumor growth promotion." (PMID 29484121, 2018). "For example, KLF12 and NFE2L2 were significantly associated with HPV(+) tumours." (PMID 28139702, 2017). "Because NFE2L2 MUs are uncommon, a large enough sample size will be necessary in the future to determine whether they are independently associated with outcomes in other tumor types." (PMID 37794491, 2023). "However, Nfe2l2-null MDSCs have higher levels of intracellular ROS that suppress CTLs proliferation and induces T-cell anergy, a state of loss of CTLs antigen recognition, resulting in the increased tumor metastasis in a xenograft model of lung cancer." (PMID 32640524, 2020). "Among these five samples, whole exome sequencing data revealed that two PDC models, 193_C and 1081_C presented the same missense mutations in NFE2L2 and KEAP1 as found in the paired tumour tissues." (PMID 39707614, 2025). "Recent studies have also found that USP13 can promote the transition of ferroptosis to autophagy in tumor cells by activating the NFE2L2/NRF2-SQSTM1/p62-KEAP1 axis in a KRAS signaling pathway-dependent manner." (PMID 40994946, 2025). "Similar to primary murine tumor and tumor-derived cell line data, patient MPNSTs showed increased expression of NFE2L2 (NRF2) (in gray)." (PMID 40802750, 2025). "Mutations in NFE2L2 and KEAP1 are also prevalent, with 84% of redox tumours exhibiting alterations in these genes." (PMID 40849356, 2025). "Gene programs regulated by both tumor suppressors include genes induced by the master oxidant-responsive transcription factor NRF2 (NFE2L2)." (PMID 40802750, 2025). "Conversely, Polycomb repressive complex 2 epigenetically silences NFE2L2 via H3K27me3 deposition in lung cancer, exerting tumor-suppressive effects." (PMID 40868167, 2025). "This crosstalk contributes to tumor adaptability and survival, making NFE2L2 a potential therapeutic target." (PMID 41179304, 2025). "In these malignancies, elevated NFE2L2 activity supports tumor progression, metastasis, and resistance to therapies." (PMID 39534872, 2024). "Activation of NFE2L2 in mouse xenograft tumour models also enhanced the expression of FTH1 and GPX4 and decreased the expression of TFRC to some extent." (PMID 38685674, 2024). "These tumours have alterations in chromosomal numbers and are associated with mutations in MET, CDKN2A, SETD2, BAP1, PBRM1, NFE2L2, and mTOR genes and have a better prognosis when compared with clear cell RCC in the organ-confined stage." (PMID 38265103, 2024). "Certain genes appeared to demonstrate a trend for site-specific mutation - for example, NFE2L2 and FBXW7 variants were exclusively detected at the tumour margin in 5 out of 8 patients and 3 out of 9 patients respectively." (PMID 38846976, 2024). "Collectively, these studies suggest that targeting MGST1, either through NFE2L2-dependent or NFE2L2-independent pathways, represents a promising strategy to enhance ferroptosis-mediated tumor suppression." (PMID 39534872, 2024).
tumor (continued). "Our results demonstrate that high NFE2L2 expression in T-ALL was accompanied by the implementation of a specific gene expression program leading to NRF2-induced signalling in tumour cells." (PMID 37373496, 2023). "In B-ALL, NFE2L2 overexpression hinders tumour sensitivity to vincristine, and this occurs through the PI3K-AKT-mTOR pathway." (PMID 37373496, 2023). "It is in line with the fact that NFE2L2 is a crucial regulator of tumor metastasis, and the downstream targets of NFE2L2 were more related to genes involved in EMT regulation." (PMID 38071219, 2023). "Once the KEAP1/NFE2L2 pathway is inappropriately active in tumor cells, it can stimulate tumor growth." (PMID 37794491, 2023). "Gene expression profiling showed that SLC31A1, LIPT2, CDKN2A, and GCSH expression was increased in tumor tissues, while NFE2L2, NLRP3, ATP7A, DLD, MTF1, and DLST expression was decreased in tumor tissues compared with normal tissues." (PMID 37065485, 2023). "Complementary observations were made from our scRNA-seq dataset where SCENIC showed that RMC tumour cells were characterized by the activation of the NFE2L2/3 regulon a major regulator of ferroptosis 35,36." (PMID 37236926, 2023). "Insufficient NFE2L2 activity leads to early tumorigenesis, whereas overactive NFE2L2 leads to tumor progression and resistance to therapy." (PMID 38130953, 2023). "Comparable observations were made between the TAL and RMC populations of the naive tumour with loss of TFCP2L1 activity and gain of MYC and NFE2L2/3 activity." (PMID 37236926, 2023). "Quantitative polymerase chain reactionanalysis of the mRNA expression in U-87 MG and SKOV-3 tumor tissuesfrom 15-treated mice showed the presence of Ptgs2/Nfe2l2/Sat1/Akr1c1/Gpx4 genes correlated with ferroptosis in bothgroups." (PMID 36395526, 2022). "The association patterns of NFE2L2 and GCSH in the tumor cell region and immune cell region of NPC are different when Jab1 is lowly expressed." (PMID 36618352, 2022). "With low expression of Jab1, NFE2L2 was negatively correlated with GCSH expression in tumor cell enriched regions, while NFE2L2 was positively correlated with GCSH expression in immune cell enriched regions." (PMID 36618352, 2022). "In addition, we observed that NRAS, MET, and NFE2L2 mutations may predict early tumor recurrence." (PMID 34543520, 2022). "NFE2L2 was lower in SCLC tissues/cells than adjacent non-tumor tissues in the GSE145907 data set and LUAD cells in the CCLE RNA-seq data set." (PMID 35453346, 2022). "In support of these results and importantly, analysis of the TCGA and SU2C PC tumor datasets demonstrated that MUC1 significantly correlates with activation of the NFE2L2.V2 signature and SLC7A11 and G6PD gene expression." (PMID 34163028, 2021). "There was a statistically significant increase in NFE2L2 mRNA expression in tumor tissue at 72 h after SDT (day 11) compared to the control animal group (p ≤ 0.0001)." (PMID 34681196, 2021). "In the univariable Cox analysis, clinical tumor stage, age, and the expression levels of NFE2L2, ITGAV, GET4, FERMT2, CRB3, CDH2, and BCL2L1 were prognostic factors for OS." (PMID 33850477, 2021). "In tumor 3D spheroids, inner, matrix-deprived cells that are under high oxidative stress, show reduced survival potential upon NFE2L2 silencing." (PMID 34685621, 2021). "By analyzing the infiltration of immune cells and the stromal score, NFE2L2 gene was found to play an important role in tumor immunity." (PMID 34281539, 2021).
tumor (continued). "SQSTM1 plays a significant role in tumor transformation due to its important function as a signaling molecule interacting with many oncogenic pathways, including those involving NFE2L2/NRF2 and NFKB/NF-κB." (PMID 34830876, 2021). "The GSEA results manifested that KEAP1/NFE2L2/CUL3 Mut group patients have a complex ROS mechanism that affects tumor development." (PMID 34617407, 2021). "For example, at early times, NFE2L2 activation can protect against oxidant-mediated DNA damage and the accumulation of oncogenic lesions and thus serve as a tumor suppressor." (PMID 33919162, 2021). "To further determine the differences in NFE2L2 expression between the tumor and normal tissues, we obtained NFE2L2 expression data from TCGA database." (PMID 33101586, 2020). "Nuclear accumulation of NRF2 and low expression of KEAP1 correlated with tumor aggressiveness, although the expected phenotypic outcomes were not necessarily consistent in cases of somatic mutation in KEAP1 vs. NFE2L2." (PMID 32938017, 2020). "When pathway analysis was carried out, alterations in those linked to oxidative stress were found in 22% of tumours due to mutations in KEAP1 (mutated in 19%), CUL3 (mutated in >1%) and NFE2L2 (mutated in 3%)." (PMID 33276631, 2020). "However, the role and underlying mechanisms of NFE2L2 in tumor immunity are unknown." (PMID 33101586, 2020). "Conversely, demethylation of a CpG island in the promoter of NFE2L2 has been identified in CRC tumour samples." (PMID 33276631, 2020). "Mutations in KEAP1 and CUL3 genes are mutually exclusive with the one in the NFE2L2 gene present in 6.6% of ccRCCs; indeed 10.4% of the tumor analyzed presented a deletion in the CUL3 locus 2q36." (PMID 33233657, 2020). "Expression levels of VEGFA, NFE2L2, miR-17-5p, and miR-612 in the tumor tissues, colloid goiter, and their respective adjacent tissues were compared to those observed in the normal tissues." (PMID 32824922, 2020). "Redox tumours are enriched for oxidation-reduction and glutathione pathways and harbor more NFE2L2/KEAP1 alterations and copy gain in the 3q2 locus." (PMID 31395880, 2019). "High level TrkB-T1 mRNA is a marker of a distinct SCC subtype enriched for at least 3 pathways relevant to tumor progression: Nfe2l2 response, retinol metabolism, and hedgehog signaling." (PMID 31221127, 2019). "One tumor cell growth-promoting mechanism is through the crosstalk between NRF2 (also known as NFE2L2) cytoprotective transcription factor and the Notch pathway." (PMID 31003475, 2019). "E2F1 and NFE2L2 overexpression values were both higher than expected by TCGA data, and even more elevated in metastasis than in primary tumours." (PMID 29743718, 2018). "Oncogenic Kras and B-Raf, Myc, the phosphoinositide 3-kinase (PI3K)-Akt pathway, and the Notch signaling pathway have also been reported to augment Nfe2l2 transcription, thus suggesting a possible mechanism for the increased expression of Nrf2 in tumor cells." (PMID 28899199, 2018). "In fact, the regulation of NFE2L2, and PTK2 expression are linked indirectly through FGF7, a member of the fibroblast growth factor family involved in wound repair and tumor development." (PMID 27812189, 2016). "Despite distinct histologies and cell contexts of source tumours, RB1 loss-of-function mutations and NFE2L2 mutations/amplifications exhibited similar expression patterns." (PMID 26436532, 2015).